TUBA8 (tubulin alpha 8)
Description:
Tubulin is the major constituent of microtubules, a cylinder consisting of laterally associated linear protofilaments composed of alpha- and beta-tubulin heterodimers. Microtubules grow by the addition of GTP-tubulin dimers to the microtubule end, where a stabilizing cap forms. Below the cap, tubulin dimers are in GDP-bound state, owing to GTPase activity of alpha-tubulin.
Synonyms: TUBAL2; CDCBM8; MACTHC2
Tractability: Small molecule: a high-quality ligand is known; it belongs to a druggable protein family. PROTAC: ubiquitination databases record sites on it; a small molecule that binds it is known.
Target class: Structural protein
Gene: Protein-coding gene on chromosome 22 (18,110,100 to 18,146,683, forward strand). Ensembl gene ENSG00000183785.
Subcellular location: Cytoplasm, cytoskeleton
Subcellular location (Human Protein Atlas): Microtubules
Pathways (Reactome):
Cell Cycle: EML4 and NUDC in mitotic spindle formation; Mitotic Prometaphase; Recruitment of NuMA to mitotic centrosomes; Resolution of Sister Chromatid Cohesion; Sealing of the nuclear envelope (NE) by ESCRT-III; Separation of Sister Chromatids; The role of GTSE1 in G2/M progression after G2 checkpoint
Vesicle-mediated transport: COPI-dependent Golgi-to-ER retrograde traffic; COPI-independent Golgi-to-ER retrograde traffic; COPI-mediated anterograde transport; Gap junction assembly; Microtubule-dependent trafficking of connexons from Golgi to the plasma membrane; Translocation of SLC2A4 (GLUT4) to the plasma membrane
Metabolism of proteins: Carboxyterminal post-translational modifications of tubulin; Formation of tubulin folding intermediates by CCT/TriC; Post-chaperonin tubulin folding pathway
Immune System: MHC class II antigen presentation; PKR-mediated signaling
Neuronal System: Activation of AMPK downstream of NMDARs; Assembly and cell surface presentation of NMDA receptors
Signal Transduction: RHO GTPases Activate Formins; RHO GTPases activate IQGAPs
Autophagy: Aggrephagy
Cellular responses to stimuli: HSP90 chaperone cycle for steroid hormone receptors (SHR) in the presence of ligand
Developmental Biology: Recycling pathway of L1
Disease: HCMV Early Events
Hemostasis: Kinesins
Organelle biogenesis and maintenance: Cargo trafficking to the periciliary membrane
Gene Ontology:
Molecular function: protein binding; GTP binding; GTPase activity; structural constituent of cytoskeleton
Biological process: mitotic cell cycle; cytoskeleton organization; microtubule-based process; spermatid development; spermatogenesis
Cellular component: microtubule cytoskeleton; acrosomal vesicle; cytoplasm; cytoskeleton; microtubule
Genetic constraint (gnomAD): Loss-of-function variants: 29 observed, 35.39 expected, observed/expected ratio (o/e) 0.82, 90% interval 0.61 to 1.12. The upper end of that interval is the gene's LOEUF score, 1.12, which puts it in group 4 of 6, group 1 being the genes least tolerant of losing a copy. Missense variants: 541 observed, 629.22 expected, observed/expected ratio (o/e) 0.86, 90% interval 0.8 to 0.92. Synonymous variants: 226 observed, 242.41 expected, observed/expected ratio (o/e) 0.93, 90% interval 0.84 to 1.04.
Gene-disease validity (ClinGen):
ClinGen rates the evidence that TUBA8 causes each of these diseases.
polymicrogyria with optic nerve hypoplasia (autosomal recessive): Disputed.
Homologues: Orthologues: chimpanzee PEX26 (99% identical), chimpanzee TUBA8 (99% identical), macaque TUBA8 (99% identical), mouse Tuba8 (99% identical), rabbit TUBA8 (99% identical), pig TUBA8 (99% identical), rat Tuba8 (99% identical), guinea pig TUBA8 (98% identical), tropical clawed frog tuba8 (88% identical), dog TUBA8 (85% identical). Paralogues in human: TUBA3C (91% identical), TUBA3D (91% identical), TUBA1A (90% identical), TUBA1B (90% identical), TUBA4A (90% identical), TUBA1C (90% identical), TUBA3E (90% identical), TUBAL3 (71% identical), TUBB (41% identical), TUBB3 (41% identical), TUBB4B (41% identical), TUBB4A (41% identical), and 11 more.
Diseases named in the same sentence as TUBA8 in open-access papers:
TUBA8 is named in the same sentence as 23 diseases in open-access papers, as found by Europe PMC text mining. Sharing a sentence is not in itself a finding about the gene and the disease. The quoted sentences say what the papers report.
polymicrogyria (5 papers, 2017 to 2023). A developmental brain abnormality characterized by an excessive amount of small convolutions on the surface of the brain and cognitive dysfunction. "Optic nerve hypoplasia has been reported in four subjects from two consanguineous families with TUBA8 mutations and polymicrogyria." (PMID 33806565, 2021). "There was also one case of polymicrogyria with optic nerve hypoplasia (TUBA8 gene mutation, p.Q235R)." (PMID 29348930, 2017). "Mutations in TUBA8 were associated with recessive polymicrogyria." (PMID 36980952, 2023). "The association between microcephaly, polymicrogyria and cerebellar agenesis prompted us to screen for tubulin genes (TUBA1A, TUBA8, TUBB2A, TUBB2B, TUBB3, TUBB4A, TUBB, TUBG1), which were all negative." (PMID 35162247, 2022). "Tubulin Alpha 8 (TUBA8) is a protein-coding gene, and diseases closely related to this gene include polymicrogyria with optic nerve hypoplasia." (PMID 35126370, 2021).
tubulinopathies (3 papers, 2017 to 2021). "Other “tubulinopathies” genes include TUBA1A, TUBB2A, TUBB2B, TUBA8, TUBB3, TUBB, and TUBG1, which were found to be DEGAs in various brain regions." (PMID 34638726, 2021). "In recent years, an increasing number of tubulin genes were linked to a clinically heterogeneous group of disorders, the “tubulinopathies” (TUBA1A, MIM#602529; TUBA8, MIM#605742; TUBB2A, MIM#615101; TUBB2B, MIM#612850; TUBB3, MIM#602661; TUBB, MIM#191130; TUBG1, MIM#191135)." (PMID 30744660, 2019).
liver cancer (2 papers, 2019 to 2023). An epithelial or non-epithelial malignant neoplasm that arises from the liver. "In mice, the TUBA8 mRNA/protein was significantly higher in the fatty liver and tumor tissues of mice and in hepatocarcinoma (liver cancer) patients." (PMID 38137937, 2023). "Up-regulation of TUBA6, TUBA8, and TUBB3 has been reported in human liver cancer." (PMID 31191608, 2019).
microcephaly (2 papers, 2018 to 2022). A congenital or acquired developmental disorder in which the circumference of the head is smaller than normal for the person's age and sex. "Microtubule structure alterations as well as alterations of binding partners necessary for proper microtubule dynamics resulting from pathogenic variants in TUBA1A, TUBB2A, TUBB2B, TUBB3, TUBB5, TUBG1 and TUBA8 genes are also responsible microcephaly and microlissencephaly." (PMID 30340542, 2018).
aneurysm (1 paper, 2009). Bulging or ballooning in an area of an artery secondary to arterial wall weakening. "Perhaps more important to the predilection of the suprarenal aorta to aneurysm formation are the downregulation of a number of genes coding for structural extracellular matrix proteins including Lama3, Myo18b and the cytoskeletal protein Tuba8." (PMID 19580648, 2009).
ankylosing spondylitis (1 paper, 2021). An autoimmune chronic inflammatory disorder characterized by inflammation in the vertebral joints of the spine and sacroiliac joints. "Dysregulation of SAA1, TUBA8 and monocytes are key factors in ankylosing spondylitis with femoral head necrosis." (PMID 35126370, 2021).
asthenozoospermia (1 paper, 2017). "Tuba8 was absent from the immature sperm shed into the lumen of the tubules; this contrasts to a recent report in which TUBA8 was described in the flagella of human spermatozoa, and was reduced in asthenozoospermia, at the RNA and protein level." (PMID 28388629, 2017).
autism (1 paper, 2017). Persistent deficits in social interaction and communication and interaction as well as a markedly restricted repertoire of activity and interest as well as repetitive patterns of behavior. "Interestingly, knockdown of H2A.Z.1, but not H2A.Z.2, led to altered expression of several candidate genes linked to psychiatric disorders such as autism and schizophrenia (Neurexin1, Shank3, CaMK2G, Vamp7, Gsk3b, Tuba8, Grm8, etc.)." (PMID 28856239, 2017).
bipolar disorder (1 paper, 2023). A disorder of the brain that causes unusual shifts in mood, energy, activity levels and the ability to carry out day-to-day tasks. "Bipolar disorder at 22q11.2 (with single genes models most often explaining variance) showed association with flanking genes on either side, TUBA8, TMEM191B, and PPIL2; PPIL2 appeared in most of the pairs, as well." (PMID 37267418, 2023). "However, we can identify five top genes at 22q11.2 associated with BMI (YDJC, CCDC116, PPIL2, THAP7, UBE2L3), primarily located outside the canonical CNV region (LCR D-E), three with bipolar disorder (TMEM191B, TUBA8, PPIL2), six with ASD (CLTCL1, AC004471." (PMID 37267418, 2023).
CEDNIK syndrome (1 paper, 2017). CEDNIK syndrome is a neurocutaneaous syndrome characterized by severe developmental abnormalities of the nervous system and aberrant differentiation of the epidermis. "Within the previously defined autozygous region predicted to contain the causative mutation, in addition to the described TUBA8 loss of function mutation, we identified a mutation in SNAP29, previously identified as the cause of CEDNIK syndrome." (PMID 28388629, 2017).
cognitive decline (1 paper, 2024). "Seven of the 22 peptides associated with the frail vs control diagnostic contrast and cognitive decline were cytoskeleton-related, including proteoforms of MAP2, VIM, TUBB, DBN1, TUBA8, PALM and NEFM." (PMID 38531951, 2024).
dementia (1 paper, 2023). Loss of intellectual abilities interfering with an individual's social and occupational functions. "In patient GC034823, who demonstrated cognitive regression and dementia, both of which are unusual for 22q11.2DS, the deletion region is expanded and encompasses the TUBA8 gene." (PMID 36980952, 2023).
tumor (3 papers, 2018 to 2023). "As result, the α-tubulin isoforms TUBA1B, TUBBA1A and TUBA1C had the highest mRNA expression levels, while TUBA4B and TUBA8 had the lowest expression level among the tubulin isoforms in all the tumor samples." (PMID 30126203, 2018). "TUBA8 is more strongly expressed in transformed cells compared to non-tumor tissues." (PMID 35126370, 2021). "The α-tubulin isoform TUBA8 and the β-tubulin isoform TUBB2B had respectively the highest and the lowest expression levels in the four tumor subtypes." (PMID 30126203, 2018).
nervous system disorder (1 paper, 2015). A non-neoplastic or neoplastic disorder that affects the brain, spinal cord, or peripheral nerves. "Recently, mutations in neuronal tubulin genes (e.g. TUBA1A, TUBB2B, TUBB3 and TUBA8) have been identified in patients suffering from nervous system disorders, underlining the importance of tubulin isotypes in MT dynamics during brain development and axon guidance." (PMID 26331477, 2015).
TUBA8 also shares sentences with these, for which no sentence is quoted: optic nerve hypoplasia (2 papers); atrial fibrillation (1); breast carcinoma (1); cerebellar agenesis (1); Lissencephaly (1); microlissencephaly (1); osteoporosis (1); psychiatric disorder (1); schizophrenia (1).